IFI6 (interferon alpha inducible protein 6)
Description:
Interferon-stimulated protein that plays an important role in innate immune response against a wide variety of viruses. Inhibits flavivirus replication by preventing the formation of virus-induced endoplasmic reticulum membrane invaginations, which are double-membrane vesicles that flaviviruses use for their replication. Has an antiviral activity towards hepatitis C virus/HCV by inhibiting the EGFR signaling pathway, whose activation is required for entry of the virus into cells. Within the nucleus, restricts hepatitis B virus/HBV promoter activity leading to substantial reduction of viral replication and gene expression. Plays a role in apoptosis, negatively regulating the intrinsinc apoptotic signaling pathway and TNFSF10-induced apoptosis. However, it has also been shown to have a pro-apoptotic activity. Modulates innate immune response mediated by RIGI by preventing its activation.
Synonyms: Ifi-6-16; G1P3; IFI616; FAM14C; 6-16
Tractability: Antibody: its Gene Ontology location is reachable by antibodies, with high confidence; UniProt predicts a signal peptide or a membrane-spanning region. PROTAC: ubiquitination databases record sites on it.
Gene: Protein-coding gene on chromosome 1 (27,666,064 to 27,672,212, reverse strand). Ensembl gene ENSG00000126709.
Subcellular location: Endoplasmic reticulum membrane; Mitochondrion inner membrane
Subcellular location (Human Protein Atlas): Mitochondria
Pathways (Reactome):
Immune System: Interferon alpha/beta signaling; Modulation of host responses by IFN-stimulated genes
Gene Ontology:
Molecular function: protein binding; molecular adaptor activity
Biological process: apoptotic process; cellular response to virus; defense response to virus; innate immune response; intrinsic apoptotic signaling pathway; negative regulation of apoptotic process; negative regulation of extrinsic apoptotic signaling pathway in absence of ligand; negative regulation of mitochondrial depolarization; negative regulation of release of cytochrome c from mitochondria; reactive oxygen species metabolic process; regulation of epidermal growth factor receptor signaling pathway; immune response
Cellular component: endoplasmic reticulum membrane; mitochondrial inner membrane; mitochondrial membrane; mitochondrion; mitochondrial outer membrane; plasma membrane; membrane
Genetic constraint (gnomAD): Loss-of-function variants: 10 observed, 9.63 expected, observed/expected ratio (o/e) 1.04, 90% interval 0.64 to 1.7. That is too few expected variants to judge how well the gene tolerates losing a copy. Missense variants: 154 observed, 153.45 expected, observed/expected ratio (o/e) 1, 90% interval 0.88 to 1.15. Synonymous variants: 89 observed, 74.28 expected, observed/expected ratio (o/e) 1.2, 90% interval 1.01 to 1.43.
Homologues: Orthologues: chimpanzee IFI6 (98% identical), macaque IFI6 (77% identical), pig IFI6 (68% identical), dog IFI6 (60% identical), zebrafish ifi27.4 (32% identical), zebrafish ifi27.6 (28% identical). Paralogues in human: IFI27L2 (35% identical), IFI27L1 (32% identical), IFI27 (31% identical).
Diseases named in the same sentence as IFI6 in open-access papers:
IFI6 is named in the same sentence as 81 diseases in open-access papers, as found by Europe PMC text mining. Sharing a sentence is not in itself a finding about the gene and the disease. The quoted sentences say what the papers report.
viral infection (56 papers, 2006 to 2026). "IFI6 is also vital for innate immunity against multiple viruses as viral infections can drive the onset of SSc in susceptible individuals." (PMID 39050259, 2024). "Chronic inflammation resulting from viral infections promotes AS development; IFI6 is associated with the type I interferon-signaling pathway, and these type I interferons in plaques are known to aggravate AS; additionally, type I interferons are essential mediators of the pathogenesis of AS." (PMID 39050259, 2024). "Remarkably, these new functions of IFI6 could be targeted to treat diseases associated with an exacerbated induction of innate immune responses and to combat viral infections, such as IAV and SARS-CoV-2." (PMID 36793726, 2023). "Furthermore, the proteins encoded by IFI6 may play an important role in the regulation of apoptosis and restrict various viral infections by targeting different stages of the viral life cycle." (PMID 36003956, 2022). "Further, IFI6 performs distinct functions in various viral infections, and it is postulated that the antiviral effects of IFI6 are specific." (PMID 39518785, 2024). "This newly discovered function of IFI6 holds promise as a therapeutic target for addressing conditions marked by overactive innate immune responses and combating viral infections." (PMID 38473938, 2024). "In contrast, a recent report showed that IFI6 can positively affect virus infection and that IFI6 overexpression results in increased influenza replication in cell cultures and in the murine model." (PMID 39024231, 2024). "In conclusion, the relevance of OAS1, IRF9, and IFI6 in controlling the viral infection was confirmed." (PMID 38731851, 2024). "To assess the effect of IFI6 in conferring biologically relevant IFN-mediated antiviral activity to virus infection, we assessed the effect of knocking-out IFI6 on viral infection." (PMID 36793726, 2023). "During the occurrence and development of viral infectious diseases, autoimmune diseases and some tumors, IFI6 is often highly expressed, which exerts the functions of resisting apoptosis and viruses, as well as promoting tumor progression." (PMID 37670388, 2023). "Several studies have assessed IFI6 role against viral infections in order to describe possible mechanisms of action." (PMID 36793726, 2023). "It was also reported that interferon response genes were also found to increase as a response to viral infections while the epithelial was infected, including IFI6 similar to our finding." (PMID 35422859, 2022). "One of the antiviral actions is that IFI6-16 was involved in regulating apoptosis with the ability to affect mitochondrial membrane potential during viral infection." (PMID 35632802, 2022). "As one of the innate immune effectors in the IFN antiviral pathway, IFI6-16 participates in apoptosis response during virus infection in vertebrates." (PMID 35632802, 2022). "Consistent with the report, we also detected that ERV_2446004 and ERV_2446045 were neighbored by APOL1, while ERV_0238545 was neighbored by IFI6; these ERVs were among the 43 pairs that were closely related to viral infections." (PMID 34009516, 2021). "Interferon-alpha inducible protein 6 (IFI6) is an IFN-stimulated gene (ISG) whose expression is highly regulated by the stimulation of type I IFN-alpha that restricts various kinds of virus infections by targeting different stages of the viral life cycle." (PMID 33868257, 2021). "ΔORF5 mutant virus infected cells survive because the virus induces a more robust innate antiviral response in these cells and the apoptotic processes that accompany W + virus infection are dampened (see IFI6 expression)." (PMID 32350357, 2020). "In addition to its well-established role in virus infection, IFI6, an IFN-stimulated gene localized in the inner mitochondrial membrane, has been shown to play a pro-oncogenic role in various tumors and is associated with ROS accumulation." (PMID 39988631, 2025).
viral infection (continued). "In addition, a negative correlation was found between IFI6 and viral load (p = 0.033) in the upper airway, suggesting that the IFI6 expression inhibits the viral infection." (PMID 39590591, 2024). "The expression of IFI6 is tightly regulated in response to IFNα stimulation and plays a crucial role in restricting viral infections including West Nile Virus, Dengue Virus, Yellow Fever, Hepatitis B and Hepatitis C viruses through interference with viral RNA synthesis and translation." (PMID 39024231, 2024). "Additionally, the RIG-I-like receptor (RLR) signaling pathway, responsible for detecting viral infections and activating immune responses, strongly correlated with IFI6." (PMID 38473938, 2024). "In addition, we find a completely novel function for IFI6 in negatively regulating innate immune responses induced after viral infections in cell cultures and in vivo." (PMID 36793726, 2023). "IFI6 plays different roles in different viral infections, and it has been speculated that the antiviral effect of IFI6 is specific." (PMID 38033564, 2023). "HERC6, IFI6, ISG15, and MX1 encode for proteins induced by type I interferons, such as IFN-α, IFN-β, IFN-ω, and are typically produced by host cells in response to viral infection." (PMID 35197051, 2022). "Researchers compared and analyzed the transcriptional data of cells with SARS-CoV-2 and other viral infections and found that IFI6 may be a potential target for intervention in COVID-19." (PMID 35928229, 2022). "In human viral infections, IFI6’s relation to host immunity appears to be disputable as two separate studies, one touting suppression of hepatitis C virus and the other study claiming IFI6 upregulation permitted hepatitis C viral entry, show the gene’s involvement in viral infections." (PMID 33187194, 2020). "However, the potential role of IFI6 and its mechanism of action in infectious diseases, especially in viral infections like DENV, remain poorly defined." (PMID 26244642, 2015). "In addition, the chicken IFI6 gene is located in a different branch than the mammalian IFI6 gene, suggesting that its function in birds during viral infection may be different from that in mammals." (PMID 38033564, 2023). "For example, overexpression of IFI6-16 inhibited genome replication and gene expression of HBV (hepatitis B virus) in HepG2 cells, and researchers also found that IFI6-16 could inhibit HCV (hepatitis C virus) infection by impairing EGFR mediated CD81 co-localization with claudin-1." (PMID 35632802, 2022). "Therefore, IFI6, which is induced by IFNα/β, may play a critical role in combating viral infection and maintaining cell survival." (PMID 26244642, 2015). "The highest ratio in this set was two-fold and out of the top 10 specificities, 7 were in the Type I interferon signature (IFITM3, MX1, IFI6, IFI44L, ISG15, OAS1, IFIT3) and one encodes a protein that is activated by dsRNA as might be present in a viral infection (EIF2AK2)." (PMID 21366908, 2011). "Several of the upregulated genes indicated a cellular response to viral infection (CXCL11, CCL8, DEFB103A, IFI6, ACOD1, and DEFB4A)." (PMID 38755665, 2024). "Meanwhile, IFI6, IFITM2, ISG15, and LDHB were highly expressed in memory CD4+T cells, which were crucial for cell hypermetabolism and defense against virus infection." (PMID 35095832, 2021). "It is relevant to consider that MSC are usually resistant to viral infection due to their expression of interferon (IFN), and, subsequently, IFN-stimulated genes (ISGs) (such as IFI6, ISG15, SAT1, PMAIP1, p21/CDKN1A, and CCL2)." (PMID 33808241, 2021). "We cloned chicken MX1, IFI6, IFIT5, RSAD2, and OASL into eukaryotic expression vector and evaluated their effects on virus infection in DF1 cells." (PMID 32183248, 2020). "Selected antiviral genes (IFI6, IFIT3 and IFITM3) were also up-regulated, indicating that PAMs were attempting to control the viral infection." (PMID 23527143, 2013).
viral infection (continued). "The observed elevation of ISGs, encompassing ISG15, IFI6, IFIT1, IFIT2, IFIT3, IFI44L, and IFITM3, highlights SARS-CoV-2’s ability to activate the host’s interferon response—a critical defence mechanism against viral infection." (PMID 39940816, 2025). "All three lncRNA-mRNA pairs, including lncRNA XLOC-022175 vs CXCL2 (co-upregulated), XLOC-019295 vs IFI6 (co-upregulated), and XLOC-017089 vs CD163 (co-downregulated) exhibited significant changes after virus infection, which coincided with the predicted correlation networks." (PMID 33711920, 2021). "Interestingly, MSC are usually resistant to viral infection due to their expression of ISGs such as IFITM, IFI6, ISG15, SAT1, PMAIP1, p21/CDKN1A, and CCL2 that preempt viral infection." (PMID 33808241, 2021). "IFNα-inducible protein 6 (IFI6, aka IFI-6-16, or GIP3) is a member of a conserved protein family that consists of IFI6, IFI27 (ISG12a), IFI27L1 (ISG12c), and IFI27L2 (ISG12b), and it was first characterized as a cellular gene induced by the IFN response and virus infections." (PMID 34205058, 2021). "IFI6 was also ectopically expressed, with the results demonstrating that the absence of IFI6 permits viral infection and its presence significantly restricts it." (PMID 34020727, 2021). "In the upregulated genes in both chMDA5 and poly(I:C) groups, many genes were ISGs, such as MX1, IFI6, IFIT5, RSAD2, OASL, and, CMPK2, which suggested that these genes might play important roles in restricting virus infection in chicken." (PMID 32183248, 2020). "Interferon is a cytokine that protects cells from viral infection and the upregulated expression of IFI27 and IFI6 might be a protective response of cancer cells to certain stresses, as well as to the upregulation of HSP expression." (PMID 27629773, 2016). "However, in addition to the functions of IFI6 and IFI27 in apoptosis, roles in viral infections have also been suggested." (PMID 23894493, 2013). "The majority of genes upregulated in HCV tumor-adjacent tissue, except IFI27, IFI6, and PLA2G2A, show average expression below 1 TPM in GTEx normal liver samples, suggesting that the upregulation of these immune-related genes in HCV tumor-adjacent tissue is likely mediated by the viral infection." (PMID 39005337, 2024). "Moreover, IFI6 (p=0.002) and OAS1 (p=0.044) were upregulated in cases with high viral loads, which could be related to protection against severe forms of this viral infection." (PMID 37389217, 2023). "We find that optimal classifiers include an interferon-stimulated gene that is strongly induced in COVID-19 compared with nonviral conditions, such as IFI6, and a second immune-response gene that is more strongly induced in other viral infections, such as GBP5." (PMID 36507688, 2023). "For example, 2′-5′-oligoadenylate synthetase like (OASL) and interferon alpha inducible protein 6 (IFI6) were significantly up-regulated in the TC-Infection group at both transcriptome and proteome datasets, which were involved in immune response during virus infection." (PMID 35154273, 2022). "Interestingly, MSC are usually resistant to viral infection due to their expression of interferon (IFN) stimulated genes (ISG) such as IFITM (interferon-induced transmembrane family), IFI6, ISG15, SAT1, PMAIP1, p21/CDKN1A, and CCL2 that preempt viral infection." (PMID 32766251, 2020). "Together, these results indicated that there were no detectable direct interactions between the IFI6 and E1 or E2 proteins that might modulate virus infection." (PMID 25757571, 2015). "The effector IFI6 does not have many proven functions in pigs, but in humans it is involved in IFN induction and signaling as part of the innate response to viral infections." (PMID 33187194, 2020). "Strikingly, canonical ISGs such as MX1, IFITM1, and IFI6 were significantly upregulated (>100-fold) in STAG2−/− HT-29 cells compared to their WT counterparts, in the absence of any virus infection." (PMID 29662124, 2018).
COVID-19 (35 papers, 2020 to 2025). A disease caused by infection with severe acute respiratory syndrome coronavirus 2. "Considering all COVID-19 patients, we observed increases in interferon-stimulated genes, including interferon alpha-inducible protein 6 (IFI6), interferon alpha-inducible protein 27, mitochondrial (IFI27)." (PMID 39161760, 2024). "Different major dysregulated biosignatures including but not limited to Interferon Alpha 1 (IFNA1), Interferon Alpha Inducible Protein 6 (IFI6), Toll-Like Receptor 4 (TLR4) and interleukin-6 (IL6) are linked to host responses to COVID-19." (PMID 39040605, 2024). "The optimal 2-gene signatures combine an interferon-stimulated gene (ISG) that is strongly induced in COVID-19, such as IFI6, with another immune response gene that is more strongly induced in other viral ARIs, such as GBP5." (PMID 36507688, 2023). "Compared to normal tissues, IFI6 is markedly upregulated in white blood cells from COVID-19 patients and nasopharyngeal tissues infected with SARS-COV-2 and is associated with antiviral immune modulation and clinical progression." (PMID 38162574, 2023). "While a protective effect of OAS1, IRF9, and IFI6 in asymptomatic and mild COVID-19 is confirmed, the role of TGFB1 and CCL5 is still controversial." (PMID 37389217, 2023). "IFI27 and IFI6 expression remained significantly elevated in COVID-19 patients likely due to an overall increase in the anti-viral response." (PMID 35477940, 2022). "The inflammatory mediator of EN-RAGE encoded by S100A12 was significantly correlated with COVID-19, and S100A8, S100A9, IRF3, IFI6, IFITM1, and IFITM3 have been reported to elicit autoinflammatory and autoimmune conditions in response to SARS-CoV-2 infection." (PMID 35172892, 2022). "IFI6 has a higher expression in moderate respect to severe COVID-19 patients, whereas ISG15 behaves viceversa." (PMID 34603282, 2021). "Notably, type I IFNs led to a significant increase in IRF3, ISG15, and IFI6 expressions in convalescent COVID-19 patients compared to healthy controls, suggesting a higher degree of activation." (PMID 35464396, 2022). "The intermediate monocytes (consistently present in COVID-19) were characterized by a pronounced antiviral, interferon-driven response, as illustrated by the upregulation of both interferon-inducible and stimulated genes (IFI6, IFI27, IFI44L, and ISG15, SIGLEC1)." (PMID 34424199, 2021). "In the present study, the differential expression of seven genes related to immunity, IRF9, CCL5, IFI6, TGFB1, IL1B, OAS1, and TFRC, was analyzed in individuals with COVID-19 diagnoses of different disease severities." (PMID 38731851, 2024). "Based on relevant results reported in the existing literature and a previous study of our group, the genes CCL5, OAS1, IRF9, IFI6, TGFB1, IL1B, and TFRC were analyzed in the present study in relation to the severity of COVID-19." (PMID 38731851, 2024). "Studies have found that IFFI44, IFI6, RSAD2, and OSAL are significantly up-regulated in COVID-19 patients and are involved in immune regulation." (PMID 36911695, 2023). "Global neutrophil expression aligned with neutrophil state-specific markers, such as interferon response genes (IFITM1, RSAD2, IFI6 and ISG10), being more highly expressed in COVID-19 neutrophils." (PMID 34782790, 2022). "We also identified that the interferon-stimulated genes (ISGs) such as IFIT2, IFI6, and IFI44L were upregulated in COVID-19 patients." (PMID 35922752, 2022). "Conventional ISGs, such as IFI6, IFI44L, LY6E, and ISG15, were markedly increased in COVID-19 patients compared to healthy controls across all major cell types in PBMCs." (PMID 35064122, 2022). "One study showed increased classical CD14+HLA-DRhi monocytes with high IFI6 and ISG15 expression in mild COVID-19 cases when compared to healthy controls, similar to our findings." (PMID 34108966, 2021).